AQP4 (aquaporin 4)
Diseases named in the same sentence as AQP4 in open-access papers (continued):
Sharing a sentence is not in itself a finding about the gene and the disease.
demyelinating disease (78 papers, 2011 to 2026). A broad group of disorders that affect the myelin sheaths that cover the neurons. "Paediatric NMOSD is a rare demyelinating disorder associated with antibodies targeting AQP4, a water channel found abundantly in the spinal cord grey matter, periaqueductal, and periventricular regions." (PMID 40729219, 2025). "In most cases, it is a demyelination disorder caused by pathogenic serum IgG antibodies against aquaporin-4 (AQP4)." (PMID 39430225, 2024). "NMOSD is a group of demyelinating disorders with autoimmune pathology targeting astrocytes that are associated with the presence of anti-aquaporin-4-IgG (AQP4-IgG)." (PMID 35865415, 2022). "This is a very interesting finding, since NMO is a demyelinating disease that is associated with antibodies against the water channel protein aquaporin-4 (AQP4) expressed on astrocytes and T helper 17 cells." (PMID 29857583, 2018). "NMOSD is characteristic of positive serum AQP4-antibody and makes it easy to find demyelinating diseases caused by astrocytic impairments more frequent." (PMID 27242432, 2016). "This contrasts with loss of AQP4 expression in NMO, a demyelinating disease in which AQP4 autoantibodies are not only a highly specific biomarker for the disease, but are involved in disease pathology as well, despite some controversy for the latter." (PMID 24252623, 2013). "In Indonesia, it is often challenging to ascertain the exact type of the demyelinating disease, because of the inability to perform a complete diagnostic workup, especially regarding the limited facilities for testing aquaporin 4 antibodies (AQP4-IgG) or anti-MOG antibodies." (PMID 34327021, 2021). "In addition, a possibility has been raised that GFAP levels could discriminate anti‐AQP4 antibody‐seropositive NMOSD from other demyelinating diseases such as anti‐MOG antibody‐associated diseases." (PMID 32495489, 2020). "MOGAD presents with a broad and age-dependent clinical spectrum, often mimicking other demyelinating disorders such as MS and AQP4+NMOSD." (PMID 41153632, 2025). "Similar sex advantage is also observed in other central demyelinating diseases such as NMOSD with positive serum AQP4 antibodies and MS, where women have higher incidence and relapse rates." (PMID 40098969, 2025). "When suspecting demyelinating disease, practitioners should order serum testing for anti-AQP4 and anti-MOG." (PMID 39741598, 2024). "NMO is an aquaporin-4 (AQP4) Ab-mediated demyelinating disease that primarily affects the optic nerve and spinal cord." (PMID 37781409, 2023). "MOG-IgA was positive in 3 of 50 patients (6%) with NMOSD, in 5 of 228 patients (2%) with other demyelinating diseases, and in 10 of 848 patients (1%) with MS who were double-seronegative for AQP4-/MOG-IgG." (PMID 37548987, 2023). "In this longitudinal study, a subgroup of patients with demyelinating disorders was double-seronegative for aquaporin 4 (AQP4) IgG and MOG-IgG but seropositive for MOG-IgA." (PMID 37548987, 2023). "Neurological syndromes associated with MOG- and AQP4-antibodies now appear as two separate demyelinating diseases, characterized by distinct pathophysiology: AQP4-NMOSD is an astrocytopathy while MOGAD currently appears as an oligodendrogliopathy." (PMID 34097296, 2022). "Antibodies against demyelinating diseases of the CNS revealed seropositive anti-aquaporin-4 antibody (AQP4-Ab)." (PMID 34559109, 2021). "NMOSD with positive-AQP4 antibody is a demyelinating disease in CNS which pathogenetic AQP4-IgG mediates and complement participates." (PMID 34194440, 2021). "Autoantibodies targeting the aquaporin-4 (AQP4) water channel protein and the myelin oligodendrocyte glycoprotein (MOG) are associated with a broad spectrum of human central nervous system (CNS) demyelinating diseases." (PMID 32625206, 2020). "MOG-IgG-related disease is now considered as a disease entity in its own right, immunopathogenetically distinct from MS and from AQP4-IgG-related demyelinating diseases." (PMID 33281728, 2020).
demyelinating disease (continued). "The results of this study have further confirmed that MOG-IgG-related neuroinflammation is immunopathogenetically distinct from classical MS and AQP4-IgG-induced demyelinating disorders." (PMID 33281728, 2020). "Anti-AQP4- and anti-MOG-antibodies are autoantibodies against glial cells that are associated with a specific spectrum of demyelinating diseases." (PMID 30364136, 2018). "Clinicians should at least be vigilant to the possible co-existence of NMO with MG, particularly in young patients with AChR-antibody-positive disease and should test for AQP4 antibodies in MG patients who develop MS or other demyelinating disorders." (PMID 26705120, 2016). "In demyelinating diseases of the central nervous system, aquaporin 4 (AQP4) and myelin oligodendrocyte glycoprotein (MOG) have emerged as interesting antibody targets." (PMID 23035757, 2012). "For example, AQP4-immunoreactivity is increased in AD and its mis-localisation is related to the formation of β-amyloid plaques, and reduced AQP4 expression has been reported in psychiatric and demyelinating disorders." (PMID 35930103, 2023). "For patients with demyelinating disease, as indicated by imaging results, CSF should be examined for anti-aquaporin-4 antibody, anti-myelin oligodendrocyte glycoprotein antibody, anti-myelin basic protein antibody, and oligoclonal bands to further clarify the diagnosis." (PMID 36523348, 2022). "NMO is a typical demyelinating disorder induced by direct autoimmune damage to astrocytic AQP4." (PMID 27242432, 2016). "Autoantibody-associated demyelinating diseases of the central nervous system such as myelin oligodendrocyte glycoprotein-antibody associated disease (MOGAD) and aquaporin 4-antibody positive neuromyelitis optica spectrum disorders (AQP4+ NMOSD) are rare diseases but can cause severe disability." (PMID 36451827, 2022). "Although both AQP4 and MOG antibody ON are antibody-mediated demyelinating diseases of the central nervous system, and both have pathogenic components of inflammation and neurodegeneration, the severity of the disease and the degree of pathogenic factors may differ between them." (PMID 34177778, 2021). "Most importantly, it indicates the need to extend the diagnosis of epilepsy towards demyelinating diseases: the determination of anti-MOG and anti-AQP4 antibodies in the serum, especially in case of focal seizures." (PMID 40137458, 2025). "The patient’s case allows us to analyze the multi-phase, clinically diverse course of MOGAD and, above all, indicates the need to expand the diagnosis of epilepsy towards demyelinating diseases: determination of anti-MOG and anti-AQP4 antibodies." (PMID 40137458, 2025). "In the future studies, comparisons of the clinical characteristics of various demyelinating diseases (e.g., MOGAD, MS, and AQP4-ab-positive NMOSD) in a multicenter cooperation and with a large sample size and long follow-up time are needed." (PMID 35669399, 2022). "To conclude, this report investigates AQP4- and MOG-specific T-cell reactivities in human individuals presenting with AQP4-Ab and MOG-Ab positive demyelinating diseases." (PMID 32625206, 2020). "During this observation period, 11 patients remained idiopathic (six had a single event, and five had recurrent demyelinating disease inconsistent with MS or NMOSD), 11 patients developed AQP4-NMOSD, seven evolved into MS, and two had an alternative diagnosis." (PMID 29064441, 2017). "Assuming a newly acquired demyelinating disorder with optic nerve involvement and afferent gait disturbance, we tested for MOG-IgG and Aquaporin 4 (AQP4) antibodies in serum and CSF, being both relevant mediators in autoimmune demyelinating syndromes of the CNS." (PMID 34266413, 2021). "Disease-modifying drugs used in MS like IFN and natalizumab should worsen NMOSD (both AQP4 positive and AQP4 negative); therefore, their use has to be carefully evaluated in other antibody-mediated demyelinating diseases." (PMID 31921724, 2019).
demyelinating disease (continued). "Anti-Myelin oligodendrocyte glycoprotein (MOG) antibodies are detected in various demyelinating diseases, such as pediatric acute disseminated encephalomyelitis (ADEM), recurrent optic neuritis, and aquaporin-4 antibody-seronegative neuromyelitis optica spectrum disorder." (PMID 28420330, 2017). "Together, the present findings suggest that caution is needed if introducing fingolimod in patients with idiopathic central nervous system demyelinating disease with atypical MS features without testing for anti-AQP4 antibodies first." (PMID 24475777, 2014). "Finally, specific antibodies (AQP4/MOG/MBP) did not detect any signs of demyelinating diseases in the central nervous system (CNS)." (PMID 34791569, 2022). "The high specificity of both AQP4 and MOG antibody assays means that in clinical practice, where there is a characteristic clinical presentation, a positive antibody result can be taken as being indicative of NMOSD or MOG antibody-related demyelinating disease respectively." (PMID 31636597, 2019). "Interestingly, Patient 5 had quite extensive T2/FLAIR signal changes spanning from C2 to C6, mimicking a demyelinating disorder but CSF restricted oligoclonal bands and anti-aquaporin 4 antibodies both tested negative." (PMID 29506874, 2018). "In previous Mayo clinic reports, Lennon and her colleagues identified patients with GFAP astrocytopathy with several additional kinds of autoantibody, including NMDAR antibody, AQP4 antibody, and MOG antibody, which suggests an immune encephalitis or demyelinating disorder." (PMID 29755396, 2018). "Thus, AQP4-NMOSD is not primarily a demyelinating disorder, but is nevertheless lumped under the MS syndrome due to clinical phenotypic similarities." (PMID 29064441, 2017). "Serum-derived autoantibodies with predominant specificity for the astrocyte water channel aquaporin-4 (AQP4) are implicated as inducers of pathology in neuromyelitis optica (NMO), a central nervous system (CNS) demyelinating disease where activated neutrophils infiltrate, unlike in MS." (PMID 26500654, 2015). "Thus, the detection of high-titer MOG-IgG might not only serve as a valuable biomarker in AQP4-IgG negative NMO and HR-NMO patients, but possibly play a role as pathogenic factor in human demyelinating diseases, although this needs to be further investigated." (PMID 22204662, 2011). "Unlike other demyelinating disorders, NMOSD involves a distinct immunopathogenesis primarily driven by aquaporin-4 antibodies (AQP4-IgG), leading to severe inflammatory damage." (PMID 41753066, 2026). "This case was negative for all other cell-based assays for AQP4 antibodies and was confirmed as positive for MOG antibodies by FACS assay and so was not considered to be a case of NMOSD, but rather as a case of MOG antibody-related demyelinating disease." (PMID 31636597, 2019). "Of note, in other case series of MG presenting with demyelinating disorders described as MS or ADEM, AQP4 testing was not reported; some of these may have represented NMO and in at least one case this was subsequently confirmed." (PMID 26705120, 2016).
Hydrocephalus (74 papers, 2007 to 2026). Hydrocephalus is an active distension of the ventricular system of the brain resulting from inadequate passage of CSF from its point of production within the cerebral ventricles to its point of absorption into the systemic circulation. "Studies have shown that mice with AQP4-deficient develop a more pronounced hydrocephalus phenotype more rapidly than wild-type mice, with reports suggesting that this deficiency results in approximately a ~70% reduction in interstitial solute clearance." (PMID 39908266, 2025). "In a model of obstructive hydrocephalus induced by kaolin injection, AQP4-deficient mice exhibited significant ventriculomegaly and increased ICP, which was suggested to result from impaired transependymal water clearance." (PMID 39944892, 2025). "Aquaporins (AQPs), especially AQP1 and AQP4, play a fundamental role in CSF dynamics and have been implicated in the pathophysiology of hydrocephalus." (PMID 40722587, 2025). "Changes in AQP4 expression and in cell-to-cell binding proteins, such as N-cadherin and Connexin 43, at the CNS/CSF interface have been associated with hydrocephalus in humans and animal models." (PMID 41226330, 2025). "Experimental models, including hop gait mice with congenital hydrocephalus and rats with hydrocephalus induced by kaolin injection into the cisterna magna, have demonstrated a close association between hydrocephalus and AQP4 expression." (PMID 41226330, 2025). "Various animal models, including hop gait mice with congenital hydrocephalus and hydrocephalus produced by injecting kaolin into the cisterna magna of rats, have demonstrated an association between hydrocephalus and AQP4 expression." (PMID 38956598, 2024). "AQP1 and AQP4 play a role in CSF production and water removal from the brain and, thus, have been implicated in the development of hydrocephalus." (PMID 39364470, 2024). "TGN-020 was used to test the association between AQP4 and hydrocephalus and iron deposition after IVH." (PMID 37208490, 2024). "In conclusion, the present study revealed that iron overload causes an upregulation of AQP4 expression in the periventricular area, which further contributes to the development of hydrocephalus after IVH." (PMID 37208490, 2024). "Abnormal AQP4 expression or distribution has been associated with hydrocephalus, a pathophysiological condition of the central nervous system (CNS) that consists of an abnormal accumulation of CSF in the intraventricular cavity." (PMID 38956598, 2024). "Our results showed, for the first time, that AQP4 in the periventricular tissue contributed to the development of hydrocephalus caused by iron overload after IVH." (PMID 37208490, 2024). "The current study investigated the role of AQP4 in the formation of hydrocephalus caused by iron overload after IVH." (PMID 37208490, 2024). "Changes in AQP4 expression and cell–cell binding proteins (such as N-cadherin and Connexin 43) at the CNS/CSF interface have been associated with hydrocephalus in humans and animal models." (PMID 38956598, 2024). "If this is maintained over time, it will cause CSF hypersecretion and AQP4 overexpression that contributes to parenchymal edema and hydrocephalus." (PMID 37397456, 2023). "This review focuses on AQP4 expression as a possible biomarker of astrogenesis development and its hypothetical relationship with pathology causing pediatric hydrocephalus." (PMID 36142348, 2022). "AQP4 plays an important role in cerebrospinal fluid (CSF) homeostasis, and alterations in its expression have been associated with hydrocephalus." (PMID 34575909, 2021). "Various animal models, including hydrocephalus with hop gait mice with congenital hydrocephalus or hydrocephalus produced by kaolin injection into the cisterna magna of rats, have demonstrated an association between hydrocephalus and AQP4 expression." (PMID 34575909, 2021).
Hydrocephalus (continued). "In fact, some antagonists of both AQP1 and AQP4 are already under investigation for their translational value in conditions in which these channels are implicated—like hydrocephalus." (PMID 30967147, 2019). "Whereas AQP4 changes have been well described in experimentally-induced hydrocephalus, few publications have studied the association between AQPs and naturally-occurring hydrocephalus." (PMID 27357498, 2016). "In light of these observations, it is conceivable that changes in Spp1 expression associated with AQP4 deficiency could affect the normal development of the aqueduct and contribute to the onset of hydrocephalus." (PMID 41226330, 2025). "These combined mechanisms may underlie, at least in part, the susceptibility to aqueductal obstruction and hydrocephalus observed in AQP4−/− animals." (PMID 41226330, 2025). "Abnormal AQP4 expression or distribution has been associated with hydrocephalus." (PMID 41226330, 2025). "Additionally, studies have shown that curcumin can modulate the expression of AQP4, a protein critical for water transport in the brain and closely linked to the development of cerebral edema and hydrocephalus." (PMID 39796474, 2024). "We speculated that AQP4 might participate in the formation of hydrocephalus caused by iron overload following IVH." (PMID 37208490, 2024). "In addition, hydrocephalus following subarachnoid hemorrhage (SAH) is caused by AQP4 dysfunction, lymphatic obstruction, and vasospasm." (PMID 39457496, 2024). "However, some researchers thought the increased AQP4 expression associated with hydrocephalus represented a compensatory response to increase brain water clearance and reduce ventricular enlargement." (PMID 37208490, 2024). "In conclusion, BM-MSC treatment in hydrocephalus can stimulate a key developmental process such as the periventricular astrocyte reaction, where AQP4 overexpression could be implicated in tissue recovery." (PMID 36982724, 2023). "AQP4 appears to play a crucial role in the edema and CSF accumulations in hydrocephalus caused by CSF extravasation through the ependyma into the interstitial fluid, which may play a protective role." (PMID 36293145, 2022). "Hydrocephalus has been linked to changes in AQP4 expression, with AQP4 being upregulated and reabsorbing some of the excessive fluid as a coping mechanism, but it remains unclear whether AQP4 accelerates or diminishes this pathology." (PMID 33499944, 2021). "AQP4 deficient mice exhibit a sporadic rate of spontaneous hydrocephalus and kaolin induced hydrocephalus in AQP4 deficient mice results in an accelerated progression of hydrocephalus." (PMID 30691235, 2019). "Animal models have implicated AQP4 in both hydrocephalus initiation and resolution." (PMID 30691235, 2019). "This increase in CSF AQP4 in hydrocephalus may occur as a consequence of the loss of communication between ependymal cells and subsequent denudation of ependyma, when AQP4 would pass into the CSF." (PMID 23659378, 2013). "AQP4 deficiency reduced cytotoxic edema produced by water intoxication, cerebral hischemia and acute bacterial meningitis, but increases vasogenic edema caused by brain tumour, cortical freeze injury, brain abscess and kaolin-induced obstructive hydrocephalus." (PMID 21119879, 2010). "Specifically, the results obtained in AQP4-deficient mice along with our data suggest that the dual regulation of AQP4 could serve as a compensatory host defense response to obstructive hydrocephalus." (PMID 21054845, 2010). "In summary, our findings suggest that the development of obstructive hydrocephalus in a small proportion of AQP4−/−/CD1 mice may be associated with a reduced presence of CD11c+ microglia and lower Spp1 (osteopontin) expression near the aqueduct of Sylvius during early postnatal development." (PMID 41226330, 2025).